GPR84 (G protein-coupled receptor 84)
Diseases named in the same sentence as GPR84 in open-access papers (continued):
Sharing a sentence is not in itself a finding about the gene and the disease.
Hyperglycemia (4 papers, 2018 to 2024). An increased concentration of glucose in the blood. "Our results showed that GPR84 deficiency in mice leads to hypoinsulinemia and type 2 diabetes symptoms of the terminal stage, along with leanness, hyperglycemia, and hyperlipidemia, under HFD feeding condition." (PMID 39512839, 2024). "In this study, Gpr84‐deficient mice exhibited type 2 diabetes symptoms including leanness, hyperglycemia, and hyperlipidemia under HFD feeding conditions, whereas no such metabolic phenotypes were observed in NC‐fed Gpr84‐deficient mice." (PMID 39512839, 2024). "Although Gpr84‐deficient mice were lean and had increased endogenous MCFAs under high‐fat diet feeding conditions, they exhibited hyperglycemia and hyperlipidemia along with lower plasma insulin and glucagon‐like peptide‐1 levels compared with wild‐type mice." (PMID 39512839, 2024). "Although Gpr84‐deficient mice were lean and had increased endogenous MCFAs under high‐fat diet feeding conditions, they exhibited hyperglycemia and hyperlipidemia along with lower plasma insulin and glucagon‐like peptide‐1 (GLP‐1) levels compared with wild‐type mice." (PMID 39512839, 2024). "We observed that GPR84 expression in murine tissues is increased by endotoxemia, hyperglycemia, and hypercholesterolemia." (PMID 29973940, 2018). "We report that GPR84 expression is upregulated in macrophages by endotoxemia, hyperglycemia, and hypercholesterolemia." (PMID 29973940, 2018). "3-hydroxy MCFAs act also as agonists to G-protein coupled receptor 84 (GPR84) which is primarily expressed in myeloid cells, and has remarkably increased expression in adipocytes when encountering acute inflammatory stimuli, and by hyperglycemia and hypercholesterolemia." (PMID 38370354, 2024). "Although the plasma glucose levels of both groups of HFD‐fed mice indicated hyperglycemia, the plasma glucose levels of HFD‐fed Gpr84−/− mice were higher than those of HFD‐fed wild‐type mice." (PMID 39512839, 2024).
liver fibrosis (4 papers, 2019 to 2025). "In conclusion, GPR84 deficiency under excess dietary fat intake accelerates lipotoxicity-induced macrophage overactivation, thereby promoting hepatic fibrosis to NASH." (PMID 36480287, 2023). "In recent years, there has been an increasing number of studies on the role of GPR84 in liver-related diseases, especially in chronic diseases such as fatty liver and liver fibrosis." (PMID 40369402, 2025). "While serum ALT and AST levels were unaffected, quantification of the Sirius Red area fraction and hepatic hydroxyproline content revealed a significant reduction of liver fibrosis, upon pharmacological treatment with the GPR84 antagonist (CpdA)." (PMID 32316235, 2020). "Thus, pharmacological inhibition of GPR84 led to significantly reduced levels of experimental steatohepatitis and liver fibrosis in vivo, to a level comparable to the ASK1 inhibitor selonsertib." (PMID 32316235, 2020). "Importantly, liver fibrosis was reduced in the GPR84 antagonist- or selonsertib-treated groups, as assessed by quantification of Sirius-Red-stained liver sections and hepatic hydroxyproline content." (PMID 32316235, 2020). "Based on our beneficial findings on inflammation and fibrosis in MCD diet and the CDAHFD-fed mice, we tested the antifibrotic effects of GPR84 antagonism in a third experimental model of liver fibrosis, based on repetitive intraperitoneal injections of CCl4, twice per week for a period of 8 weeks." (PMID 32316235, 2020). "Among the seven potential biomarkers FABP3, GALNT5, GPR84, ITGB6, MYEOV, PLEKHS1, and STRA6, we are particularly interested in GPR84 and STRA6 because they link to liver fibrosis that is a major risk factor in HCC and an independent risk factor of recurrence after hepatectomy." (PMID 31828095, 2019). "Moreover, expression of GPR84 was not detectable on hepatic stellate cells (HSC), the key matrix-producing cell type responsible of liver fibrosis progression, supporting that the antifibrotic effects of GPR84 antagonists were related to their inhibition of myeloid cells (and not HSC directly)." (PMID 32316235, 2020). "Moreover, targeted GPR84 treatment has been shown to be effective in liver fibrosis." (PMID 31828095, 2019). "Therefore, GPR84 enables the promotion of liver fibrosis and is deleterious in chronic liver disease, which may be the cause of pathogenesis and progression in HCC." (PMID 31828095, 2019). "Thus, GPR84-positive BM-derived macrophages may prevent hepatic fibrosis." (PMID 36480287, 2023). "In this study, we set out experiments to decipher the role of GPR84 in the pathogenesis of NAFLD and to explore the potential of therapeutically targeting GPR84 against NASH and liver fibrosis." (PMID 32316235, 2020). "While the toxic injury in the CCl4 model was unaffected according to histology or ALT levels, liver fibrosis was markedly reduced upon GPR84 or ASK1 inhibition, based on Sirius-Red-staining (* p = 0.084 upon GPR84 treatment) and hepatic hydroxyproline content." (PMID 32316235, 2020). "In contrast, MCFA, MCT, and GPR84 agonist administration effectively improved NASH progression by suppressing hepatic fibrosis without influencing hepatic steatosis by fat accumulation." (PMID 36480287, 2023). "Under high-fat diet (HFD) conditions, GPR84-deficient mice exhibited nonalcoholic steatohepatitis (NASH) and the progression of hepatic fibrosis but not steatosis." (PMID 36480287, 2023).
Sepsis (4 papers, 2020 to 2025). Sepsis is defined as life-threatening organ dysfunction caused by a dysregulated host response to infection. "There are few shared hub-associated entities between adult and pediatric Sepsis, with the exception of GPR84-associated EXOSC4 and ENTPD7, CD177-associated DDAH2 and MYL9-associated TGFB1l1." (PMID 32318053, 2020). "There was association of TDRD9 with CD177 and GPR84 in adult and pediatric sepsis." (PMID 32318053, 2020). "Unexpectedly, the prognosis of sepsis was significantly associated with four of the five hub genes: HK3, GPR84, CLEC4D, and S100A12." (PMID 40821971, 2025). "The profile is somewhat similar in pediatric sepsis with connections between GPR84 and TDRD9 directly and indirectly through instead DDAH2 and with CD177 through C19orf59 and RGL4." (PMID 32318053, 2020). "In adult sepsis there is indirect interaction between GPR84, CD177, and TDRD9 through EXOSC4 and with CD177 through NECAB1." (PMID 32318053, 2020). "The precise nature and detail of these differ between each of the disease processes e.g., the interactions associated with GPR84 appear inhibitory in adult sepsis and stimulatory in SIRS and pediatric sepsis." (PMID 32318053, 2020). "CD177 also exhibited strong direct connections to other hub entities GPR84 and TDRD9 in adult and pediatric sepsis and to GPR84 alone in pediatric septic shock and resolved SIRS." (PMID 32318053, 2020). "Comparing the overall interaction responses of the immune-related clusters CD177, GPR84, and KLRK1, stimulatory responses were observed between KLRK1 and its associated genes in adult sepsis, adult SIRS, pediatric SIRS and pediatric resolved SIRS." (PMID 32318053, 2020). "Finally, ANKRD22, GPR84, GYG1, BLOC1S1, CARD11, NOG, and LRG1 were recognized as critical genes associated with sepsis molecular subtypes." (PMID 36035194, 2022). "This study identified four hub genes (CLEC4D, GPR84, S100A12, and HK3) with significant prognostic value in sepsis and predicted a ceRNA network (NEAT1-hsa-miR-495-3p-ELF1) regulating their expression." (PMID 40821971, 2025). "In GSE154918 and GSE69063 datasets, ANKRD22, GPR84, GYG1, BLOC1S1, and LRG1 were all highly expressed in sepsis patients, whereas NOG and CARD11 were dramatically decreased in sepsis patients." (PMID 36035194, 2022). "Amongst the clusters in the maps, cluster MYL9, GPR84, and SLC16A3 showed uni- and/or bi-stimulatory signals in most groups, with the exception of adult sepsis which exhibited inhibitory signals." (PMID 32318053, 2020). "Gene entities shared between sepsis and severe sepsis response hubs are; TDRD9 – LIN7A, GPR84 – ENTPD7, PYCT1A and ZDHHC19, CD177 – DDAH2 and RGL4, SLC16A3 – DENND3 and MBD6, MYL9 – CMTM5, ITGB3, ITGA2B, NRGN, SELP and TREML1." (PMID 32318053, 2020). "Similar profiles for GPR84 and CD177 were observed with the overlapped genes in sepsis (adult and pediatric–TDRD9) and in SIRS (adult compared with pediatric)." (PMID 32318053, 2020). "In adult sepsis, genes TDRD9, GPR84, and CD177 interacted via overlapped genes EXOSC4 (TDRD9 ↔ GPR84 ↔ CD177), ZDHHC19 (TDRD9 ↔ CD177) and NECAB1 (GPR84 ↔ CD177)." (PMID 32318053, 2020). "GPR84 stimulates more proinflammatory processes in adult SIRS, pediatric SIRS, pediatric resolved-SIRS, pediatric sepsis, and pediatric septic shock and would support the premise that these patients exhibit profiles consistent with an ongoing pro-inflammatory immune response." (PMID 32318053, 2020). "The majority of these clusters were not connected in most disease and control states, except for adult sepsis and adult SIRS with the gene clusters for TDRD9, CD177, GPR84, PCOLCE2, FGF13 and SLC16A3 interconnected at various points, either directly or through overlapped gene connections." (PMID 32318053, 2020).
Sepsis (continued). "There are remarkable differences in ANKRD22, GPR84, GYG1, BLOC1S1, CARD11, NOG, and LRG1 gene expression and enriched pathways among different molecular subgroups of sepsis, which may be the key factors leading to the heterogeneity of clinical symptoms and prognosis in patients with sepsis." (PMID 36035194, 2022).
Alzheimer disease (3 papers, 2017 to 2023). A progressive, neurodegenerative disease characterized by loss of function and death of nerve cells in several areas of the brain leading to loss of cognitive function such as memory and language. "Based on the role of GPR84 in modulating the microglial tolerance-like state, further studies may target GPR84 for the treatment of neurological disorders that are highly associated with neuroinflammation, such as Alzheimer’s disease and Parkinson’s disease." (PMID 37190515, 2023). "Our findings show that GPR84 agonist-mediated signaling affects morphology and motility of microglia, suggesting that microglial GPR84 could be a therapeutic target in microglia-associated diseases such as multiple sclerosis and Alzheimer’s disease." (PMID 28974234, 2017). "Investigators have concluded that GPR84 exerts a beneficial action in Alzheimer’s disease by promoting microglial recruitment and preventing cognitive decline." (PMID 33281117, 2020). "Other papers also reported GPR84 up-regulation in microglia in a mouse model of endotoxemia, experimental autoimmune encephalomyelitis, and Alzheimer’s disease." (PMID 28974234, 2017).
esophageal cancer (3 papers, 2023 to 2025). A primary or metastatic malignant neoplasm involving the esophagus. "In the orthotopic esophageal cancer model, GPR84 deficiency blocked tumor progression and inhibited body-weight loss." (PMID 37105980, 2023). "We also found that PD-L1 was positively correlated with GPR84 in MDSCs from the peripheral blood of esophageal cancer patients." (PMID 37105980, 2023). "Taken together, these data suggest that GPR84 is negatively correlated with the prognosis of esophageal cancer and it enhanced MDSCs immunosuppressive characteristics in ESCC microenvironment." (PMID 37105980, 2023). "Immunofluorescence results demonstrated that GPR84 deficiency blocked MDSCs infiltration and restored CD8+ T cells aggression in esophageal cancer microenvironment." (PMID 37105980, 2023). "Then the analysis of spleen cells from esophageal cancer mice showed that GPR84 is dominantly expressed on MDSCs, but barely expressed on B cells, T cells, and NK cells." (PMID 37105980, 2023). "GPR84 antagonist or dimethyl sulfoxide (DMSO) treatment was started on day 113 after 4-NQO challenge in orthotopic esophageal cancer." (PMID 37105980, 2023). "Then we also found that immunosuppressive molecules were inhibited in MDSCs derived from GPR84−/− esophageal cancer mice." (PMID 37105980, 2023). "Overall survival analysis in patients with esophageal cancer from The Cancer Genome Atlas (TCGA) database also showed that patients with high GPR84 expression had a worse prognosis than did those with low GPR84 expression." (PMID 37105980, 2023). "With the neutralization of GM-CSF and G-CSF, we found that the expression of GPR84 and immunosuppressive molecules induced by esophageal carcinoma supernatant were both reversed." (PMID 37105980, 2023). "Additionally, GPR84 was found to be negatively correlated with the prognosis of esophageal cancer and to be overexpressed on myeloid-derived suppressor cells, which were discovered to accumulate in this disease." (PMID 39859206, 2025). "Consequently, GPR84 antagonism significantly enhanced the therapeutic success of anti PD-1 immunotherapy in the LLC/B16 esophageal cancer model." (PMID 39859206, 2025). "Therefore, targeting GPR84 enhanced anti-PD-1 efficacy in esophageal cancer and other malignant tumors." (PMID 37105980, 2023). "Furthermore, it was found that the percentage of GPR84+ MDSCs clearly increased during the development of esophageal cancer following 4-NQO challenge." (PMID 37105980, 2023). "Moreover, flow cytometry results showed that MDSCs were reduced and CD8+ T cells increased in blood and spleen of GPR84−/− esophageal cancer mice." (PMID 37105980, 2023). "Among them, GPR84 had the highest expression levels in esophageal carcinoma." (PMID 37105980, 2023). "In addition, GPR84+MDSCs and PD-L1+MDSCs were highly accumulated in anti-PD-1 therapy-resistant patients with esophageal cancer, and high GPR84 signature risk was verified as a negative factor for the overall survival of patients with anti-PD-1 treatment." (PMID 37105980, 2023). "To further verify the GPR84 expression and distribution, we downloaded the single-cell sequencing data of esophageal cancer (GSE145370) and found that the distribution of GPR84 and CD11b were highly consistent and it barely expressed on T cells." (PMID 37105980, 2023). "Moreover, the expression levels of GPR84 were remarkably higher in purified MDSCs than in purified CD4+ and CD8+ T cells from esophageal cancer tissues, suggesting that GPR84 was specifically highly expressed on MDSCs in patients with ESCC." (PMID 37105980, 2023).
experimental autoimmune encephalomyelitis (3 papers, 2008 to 2020). An autoimmune demyelinating disease of the central nervous system that is produced experimentally in animals by the injection of homogenized brain or spinal cord in Freund's adjuvant. "GPR84 was highly expressed in microglial cells in mice that manifested experimental autoimmune encephalomyelitis (EAE) and endotoxemia." (PMID 33281117, 2020). "Microglia also expressed high levels of Gpr84 in the experimental autoimmune encephalomyelitis model of multiple sclerosis." (PMID 18442421, 2008). "However, this correlates with the previously reported high Gpr84 expression in microglia in different disease models such as endotoxemia, experimental autoimmune encephalomyelitis, Alzheimer, and neuronal injury." (PMID 29973940, 2018).
Hepatic steatosis (3 papers, 2020 to 2023). Steatosis is a term used to denote lipid accumulation within hepatocytes. "We next investigated the molecular mechanisms underlying the protective activity of GPR84 against the progression of HFD-induced hepatic steatosis to fibrosis." (PMID 36480287, 2023). "In a dietary model of obesity, GPR84-deficient mice developed reduced hepatic steatosis compared to wildtype mice, upon exposure to long-chain fatty acids." (PMID 32316235, 2020). "Interestingly, in a prior study, GPR84-deficient mice developed reduced hepatic steatosis compared to wildtype mice, supporting a metabolic disease-promoting role of MCFA-GPR84 signaling in the context of NAFLD." (PMID 32316235, 2020). "Thus, GPR84 deficiency accelerates the progression from HFD-induced hepatic steatosis to NASH." (PMID 36480287, 2023). "In particular, pharmacological inhibition of GPR84 had very little (if any) effects on hepatic steatosis, which was possibly explained by the fact that GPR84 expression on hepatocytes was low." (PMID 32316235, 2020). "Histological scoring by an independent and blinded expert pathologist (Histalim) revealed variably ameliorated hepatic steatosis, ballooning, and lobular inflammation, upon pharmacological inhibition of GPR84 and ASK1, resulting in a significantly reduced NAFLD Activity Score (NAS), overall." (PMID 32316235, 2020). "To determine how GPR84 deficiency affects the liver, we induced chronic inflammation and hepatic steatosis through long-term (12 weeks) feeding of an HFD to WT and Gpr84–/– mice." (PMID 36480287, 2023). "Although PBI-4547 upregulated UCP’s, adiponectin and stimulated FAO, its effect on hepatic steatosis seems independent of GPR84 since KO mice developed similar levels of steatosis upon HFD-feeding." (PMID 32728158, 2020). "Thus, GPR84 activation by dietary MCFAs (C10:0 and C12:0, but not C8:0) markedly improves NAFLD, thereby suppressing the progression of NAFL to NASH, but not to hepatic steatosis." (PMID 36480287, 2023).
inflammatory bowel disease (3 papers, 2022 to 2023). A spectrum of small and large bowel inflammatory diseases of unknown etiology. "GPR84 is an immune cell–expressed, proinflammatory receptor currently being assessed as a therapeutic target in conditions including fibrosis and inflammatory bowel disease." (PMID 35427647, 2022). "Although this study was performed only in mouse models, another GPR84 selective antagonist, PBI-4050, has been used in phase II clinical trials to treat inflammatory bowel disease." (PMID 37105980, 2023).
multiple sclerosis (3 papers, 2008 to 2020). A progressive autoimmune disorder affecting the central nervous system resulting in demyelination. "As a membrane-bound receptor, GPR84 is markedly upregulated in macrophages and microglia in mediating the production and maintenance of inflammatory mediators in neuropathic pain, and in mice suffering from endotoxemia or multiple sclerosis, microglia express GPR84 in a strong and sustained manner." (PMID 33281117, 2020).
nonalcoholic fatty liver disease (3 papers, 2020 to 2025). "GPR84 expression was also increased in livers of patients with nonalcoholic fatty liver disease (NAFLD)." (PMID 34943862, 2021).